LINC01619 (long independently transcribed non-coding RNA 1619)
Synonyms: C12orf79
Gene: Long non-coding RNA gene on chromosome 12 (91,984,976 to 92,142,914, reverse strand). Ensembl gene ENSG00000257242.
Diseases named in the same sentence as LINC01619 in open-access papers:
LINC01619 is named in the same sentence as 2 diseases in open-access papers, as found by Europe PMC text mining. Sharing a sentence is not in itself a finding about the gene and the disease. The quoted sentences say what the papers report.
non-small cell lung carcinoma (1 paper, 2024). A group of at least three distinct histological types of lung cancer, including non-small cell squamous cell carcinoma, adenocarcinoma, and large cell carcinoma. "LINC01619 has been described to be up regulated in non-small cell lung cancer enhancing cell viability, cloning ability and stemness, which is characterized by an increased number of ALDH + cells." (PMID 39217365, 2024).
LINC01619 also shares sentences with these, for which no sentence is quoted: viral infections (1 paper).